CHRD (chordin)
Description:
Dorsalizing factor. Key developmental protein that dorsalizes early vertebrate embryonic tissues by binding to ventralizing TGF-beta family bone morphogenetic proteins (BMPs) and sequestering them in latent complexes (By similarity).
Tractability: Antibody: UniProt places it where antibodies can reach, with medium confidence; UniProt predicts a signal peptide or a membrane-spanning region; its Gene Ontology location is reachable by antibodies, with medium confidence.
Gene: Protein-coding gene on chromosome 3 (184,379,381 to 184,390,736, forward strand). Ensembl gene ENSG00000090539.
Subcellular location: Secreted
Gene Ontology:
Molecular function: protein binding; BMP binding; cytokine binding; heparan sulfate proteoglycan binding; heparin binding; syndecan binding
Biological process: BMP signaling pathway; negative regulation of BMP signaling pathway; negative regulation of cell migration; negative regulation of osteoblast differentiation; positive regulation of cell adhesion; positive regulation of mesenchymal cell proliferation; spinal cord dorsal/ventral patterning; dorsal/ventral pattern formation; floor plate development; skeletal system development; artery morphogenesis; cell population proliferation; chordate pharynx development; cranial skeletal system development; descending aorta development; embryonic axis specification; embryonic heart tube development; epithelial cell fate commitment; exploration behavior; fibroblast growth factor receptor signaling pathway; gene expression; in utero embryonic development; long-term synaptic potentiation; maintenance of protein location; mesenchymal cell fate commitment; and 12 more
Cellular component: extracellular region; cell surface; presynapse
Genetic constraint (gnomAD): Loss-of-function variants: 68 observed, 109.07 expected, observed/expected ratio (o/e) 0.62, 90% interval 0.51 to 0.76. The upper end of that interval is the gene's LOEUF score, 0.76, which puts it in group 3 of 6, group 1 being the genes least tolerant of losing a copy. Missense variants: 1,194 observed, 1,264.5 expected, observed/expected ratio (o/e) 0.94, 90% interval 0.9 to 0.99. Synonymous variants: 561 observed, 526.79 expected, observed/expected ratio (o/e) 1.06, 90% interval 0.99 to 1.14.
Gene-disease validity (ClinGen):
ClinGen rates the evidence that CHRD causes each of these diseases.
congenital heart disease (autosomal recessive): Limited. A heart disease that is present at birth.
Homologues: Orthologues: chimpanzee CHRD (99% identical), macaque CHRD (97% identical), dog CHRD (92% identical), pig CHRD (90% identical), mouse Chrd (86% identical), rat Chrd (85% identical), guinea pig CHRD (81% identical), rabbit CHRD (61% identical). Paralogues in human: MUC5B (21% identical), MUC5AC (21% identical), FCGBP (19% identical), OTOG (18% identical), VWF (18% identical), OTOGL (17% identical), ZAN (16% identical), MUC6 (15% identical), MUC2 (14% identical), TECTA (14% identical), MUC19 (13% identical), KCP (13% identical), and 7 more.
Diseases named in the same sentence as CHRD in open-access papers:
CHRD is named in the same sentence as 25 diseases in open-access papers, as found by Europe PMC text mining. Sharing a sentence is not in itself a finding about the gene and the disease. The quoted sentences say what the papers report.
ovarian carcinoma (5 papers, 2009 to 2023). A malignant neoplasm originating from the surface ovarian epithelium. "CHRD was found to be significantly under-expressed in ovarian cancer compared to normal tissues suggesting its potential of regulating BMP activity in normal ovarian surface epithelium physiology." (PMID 31973134, 2020). "Previous results using Noggin and Chordin support the potential therapeutic role of these antagonists in ovarian cancer progression through the inhibition of BMP signaling." (PMID 19366455, 2009). "Preliminary results shown here with Noggin and by others using Noggin and Chordin support the potential therapeutic role of these antagonists in ovarian cancer progression through the inhibition of BMP signaling." (PMID 19366455, 2009). "In ovarian carcinomas, BMP antagonist Chordin, was found to enhance cell adhesions and reduce tumour motility to markedly suppress tumour progression." (PMID 37688374, 2023). "CHRD, NKX2-5 were also co-expressed in bladder and ovarian cancer datasets whereas BAMBI was only reported in breast and lung datasets." (PMID 31973134, 2020). "For example, our data show that chordin (CHRD), a BMP extracellular regulator that behaves as suppressor of tumorigenesis in ovarian carcinoma cells, is abundantly expressed and regulated by PAX8 in FT194 cells, while is almost absent in SKOV-3 cells." (PMID 27259239, 2016).
gastric cancer (3 papers, 2018 to 2025). A primary or metastatic malignant neoplasm involving the stomach. "The result suggests a limited role of Chordin, Follistatin, and Noggin in regulation of BMP signaling in gastric cancer." (PMID 29720137, 2018). "Chordin (encoded by CHRD) has been identified as a negative prognostic factor in CRC and several other cancers, including lung, cervical, urothelial, renal, and stomach cancers, and is correlated with significantly lower survivability." (PMID 40212011, 2025).
holoprosencephaly (3 papers, 2016 to 2023). Holoprosencephaly (HPE) is a complex brain malformation resulting from incomplete cleavage of the prosencephalon, occurring between the 18th and 28th day of gestation, and affecting both the forebrain and face, which results in neurological manifestations and facial anomalies of variable severity. "Defective expression of physiological BMP antagonists such as Chordin and Noggin disrupted the development of the rostral neural ectoderm and downstream malformations in the forebrain on a spectrum including cyclopia, holoprosencephaly, and truncated rostral brain." (PMID 33562570, 2021). "In mice, a compound knock-out of two BMP antagonists, chordin and noggin, resulted in severe forebrain defects presenting cases of HPE with cyclopia but also more severe cases with aprosencephaly." (PMID 37175759, 2023).
Atrophy (2 papers, 2013 to 2015). Any weakening or degeneration, especially through lack of use. "Taken together, this shows that the role of CHRD in the development of atrophy and GC in humans deserves further study." (PMID 24119614, 2013).
breast carcinoma (2 papers, 2019 to 2025). "Moreover, amplification and/or upregulation of BMPs as well as BMP-antagonists, including NOG, GREM1, GREM2, and CHRD have been reported in breast cancer." (PMID 31694641, 2019).
Di George syndrome (2 papers, 2019 to 2020). "In addition, in mice with knockout of the gene encoding chordin, a phenotype was observed that is characteristic of Di George syndrome in humans." (PMID 30538173, 2019). "Mice lacking Chrd—which encodes chordin, i.e., an antagonist of bone morphogenetic proteins (BMPs)—exhibit recapitulating phenotypes of DiGeorge syndrome and Tbx1-deletion mice." (PMID 32850826, 2020).
melanoma (2 papers, 2011 to 2020). A malignant, usually aggressive tumor composed of atypical, neoplastic melanocytes. "The cell cycle and taste transduction gene sets were enriched in high-expression groups of ARHGAP6 and ADAMTS15, respectively, whereas primary immunodeficiency and melanoma were enriched in the CHRD and SPOCK1 high-expression groups, respectively." (PMID 32218218, 2020). "To analyse a potential regulation of CTGF gene expression by BMPs, we incubated Mel Im melanoma cells with recombinant BMP4, BMP7 or the BMP inhibitors noggin and chordin, respectively." (PMID 21673687, 2011).
stomach carcinomas (2 papers, 2024 to 2025). "These genes, plus CHRD, are amplified in the DNA of specific cancers such as lung squamous cell, and renal and stomach carcinomas, the latter of which are related to poor patient survival with increased CHRD expression." (PMID 38396603, 2024).
Cachexia (1 paper, 2023). Severe weight loss, wasting of muscle, loss of appetite, and general debility related to a chronic disease. "We found that there is a mild negative correlation between BMP7 expression (52% homology with gbb) and CHORDIN (CHRD, 40% homology with Sog) in cancers commonly associated with cachexia as well as non‐cachectic cancers, where the correlation is slightly strongly in the cachexia‐related cancers." (PMID 38014610, 2023). "As such, CHRD may also be relevant for the progression of cachexia in humans, thus it would be interesting to explore whether circulating CHRD can serve as a potential biomarker for the diagnosis of cachexia." (PMID 38014610, 2023).
Cornelia de Lange syndrome (1 paper, 2018). A rare syndrome characterized by low birth weight, delayed growth, intellectual disabillity, behavioral problems, and a distinctive facial appearance (thin, arched eyebrows, low set ears, small teeth, and small nose). "CHRD, chordin, is a highly-conserved developmental protein which inhibits the ventralizing activity of bone morphogenetic proteins, is active during gastrulation, expressed in fetal and adult liver and cerebellum, and is associated with Cornelia de Lange syndrome." (PMID 29670507, 2018).
fibrosarcoma (1 paper, 2023). A malignant mesenchymal fibroblastic neoplasm affecting the soft tissue and bone. "First, we compared time and dose dependent effects of DnaD and ChrD on the viability of two human mesenchymal cell types, normal dermal fibroblasts (NDF) and human fibrosarcoma cell line HT1080." (PMID 37855682, 2023).
infiltrating urothelial bladder carcinoma (1 paper, 2020). "GLI1 showed a significant level of co-expression in mucinous breast carcinoma and ovarian serous surface papillary carcinoma, whereas AMHR2, CHRD, and ACVR2A showed a similar pattern in ovarian serous papillary carcinoma, superficial bladder carcinoma and infiltrating urothelial bladder carcinoma." (PMID 31973134, 2020).
metastatic prostate carcinoma (1 paper, 2023). A carcinoma that arises from the prostate gland and has spread to other anatomic sites. "Unlike ligands, soluble antagonists in metastatic prostate cancer patients are consistently increased in patients with CHRD at 12%, NOGGIN, SOSTDC1, FSTL1 at 7% and GREM2 at 6% of patients." (PMID 36054271, 2023).
renal fibrosis (1 paper, 2024). A final common manifestation of a wide variety of chronic kidney diseases characterized by glomerulosclerosis and tubulointerstitial fibrosis. "The chordin proteins are antagonists to bone morphogenetic /transforming growth factor-beta (BMP/TGF-beta) signaling and are a critical mediator to renal fibrosis, inflammation and apoptosis after kidney injury." (PMID 39695715, 2024).
cancer (8 papers, 2015 to 2025). A tumor composed of atypical neoplastic, often pleomorphic cells that invade other tissues. "Over 70% of multiple cancer types including lung squamous cell carcinoma, uterine carcinoma, and oesophageal carcinoma patients have increased CHRD copy number variants (CNVs)." (PMID 40212011, 2025). "We previously characterized the effect of several known anti-cancer agents differing in their binding to DNA in their ability to cause DnaD, ChrD and compromise tumor cell viability to understand why some compounds cause ChrD and others cause DnaD or both, ChrD and DnaD." (PMID 37855682, 2023). "It is noteworthy that although many BMP antagonists have been identified, only a few are being researched in the context of cancer: Noggin, Gremlin and, to a lesser extent, Chordin, Sclerostin and PRDC." (PMID 32486027, 2020). "PRDC, a GREM1 homologue showing strong resemblance to Noggin and Chordin as well, was recently connected to cancer progression." (PMID 32486027, 2020). "Importantly, anti-cancer activity of both compounds was similar, suggesting that anti-cancer efficacy depends on ChrD, while the toxicity on DnaD." (PMID 37855682, 2023). "TWSG1 binds BMPs and their antagonist Chordin to control BMP signaling during embryonic development, kidney regeneration and cancer." (PMID 38862520, 2024). "As with Chordin, Chordin‐like 1 (encoded by CHRDL1) is also a negative prognostic marker in several cancer types." (PMID 40212011, 2025). "BMP7v is the only reported systemically available BMP in the context of cancer therapy and, when combined with a marked reduction in binding to endogenous BMP inhibitors such as chordin, chordin-like 2 and noggin represents a potentially significant advance in the field." (PMID 25919028, 2015). "Its role in cancer progression is not yet known; however, wild-type CHRD may have a positive effect due to its regulatory role in the signaling pathway." (PMID 38539520, 2024).
tumor (6 papers, 2009 to 2023). "Both ChrD and DnaD decreased the viability of tumor cells more than normal cells, although this relationship was reversed for bleomycin at lower concentrations." (PMID 37855682, 2023). "DnaD and ChrD are both cytotoxic; and tumor cells are more sensitive to both types of damage than normal cells." (PMID 37855682, 2023). "Similar to anthracyclines, curaxins have demonstrated anti-tumor activity in multiple preclinical models (i.e. have higher toxicity to tumor cells than normal cells), suggesting that tumor cells are more sensitive to ChrD than normal cells." (PMID 37855682, 2023). "In this study, we identified the commonalities and differences in the response of normal and tumor cells to DnaD and ChrD." (PMID 37855682, 2023). "Further, hsa-miR-532-3p along with hsa-miR-139 are associated with CHRD, FLAD1, MT1JP, and EBF2 in our analysis and have been identified as tumor suppressors in HCC that inhibit cell proliferation, migration, and invasion." (PMID 32228601, 2020). "It will be of great interest to test Noggin, Chordin, Cerberus or Gremlin as in vivo potential tumor suppressors in xenograph models." (PMID 19366455, 2009).
CHRD also shares sentences with these, for which no sentence is quoted: endometritis (1 paper); fibrosis (1); Hepatic steatosis (1); liver fibrosis (1); pemphigus vulgaris (1); polycystic kidney disease (1); primary immunodeficiency (1); schwannoma (1); soft tissue tumors (1).